IRF7 (interferon regulatory factor 7)
Diseases named in the same sentence as IRF7 in open-access papers (continued):
Sharing a sentence is not in itself a finding about the gene and the disease.
viral infection (continued). "The Irf7-/- mouse model showed severe impairment of type I IFN expression in fibroblasts upon viral infections, suggesting that IRF7 is an important regulator of the IFN induction." (PMID 26186542, 2015). "During the time-course of viral infection, the total IRF7 remained unchanged and actin was used as the internal loading control." (PMID 24722640, 2014). "Based on the two-step positive-feedback loop model for IFN production, IFN-β and IFN-α4 are produced upon virus infection at the first step and secreted to induce IRF7 expression." (PMID 24901990, 2014). "Our results show that MEFs lacking 4E-BP1 or 4E-BP2 have enhanced type-I IFN production, higher resistance to viral infection, and increased IRF-7 5′UTR-reporter gene translation as compared to WT cells." (PMID 25531441, 2014). "Consistent with our previous report that OASL1 specifically inhibits the translation of IRF7 mRNA upon viral infection, IRF7 protein levels were much higher in Oasl1 KO cells during the days, whereas IRF3 protein levels were similar between WT and KO spleens." (PMID 23874199, 2013). "Previous studies have demonstrated that viral infections can induce the nuclear translocation of IRF7 in transfected cells and in purified pDCs." (PMID 24009514, 2013). "Npro also interferes with the function of IRF7 in pDC and thus dampens interferon-α induction during viral infection." (PMID 24146623, 2013). "The mRNAs encoding IFNβ-dependent genes, such as IRF7, IFNα4, and IFNα6, as well as CXCL10 an established marker of viral infection, were also suppressed in DEAF1−/− MEFs." (PMID 23846693, 2013). "In contrast to IRF7, knockdown of IRF3 did not affect the viral production even though IRF3 and IRF7 are considered to play essential roles in innate immune responses to virus infections." (PMID 23555825, 2013). "Taken together, these data show that poly I∶C–induced stochastic IFNβ expression depends on the abundance of both poly I∶C and signaling pathway protein MDA5 as well as IRF3/IRF7, which is similar to what was found in the case of virus infection." (PMID 22291574, 2012). "At early times (6–12 h after virus infection), promoter occupancy by IRF3 and IRF7 is associated with transient recruitment of GCN5 and virus-induced histone H3K9 and H3K14 acetylation of IFN-A gene promoters." (PMID 22685561, 2012). "We also determined the dynamics of IRF3 and IRF7 recruitment to the IFN-A gene promoters in the course of virus infection." (PMID 22685561, 2012). "Understanding how EBV escapes the IRF7/IFN signaling pathway but retains IRF7's oncogenic activity is of great interest, as their outcomes shape not only the immune response to viral infection, but also affect aspects of host cell proliferation and survival." (PMID 21429244, 2011). "IRF7 is activated in the presence of double stranded RNA following virus infection, which is functional as one of the regulators of the IFN-α/β gene promoter and the IFN-α/β responsive genes to create an antiviral state." (PMID 21345237, 2011). "Lung cancer cells can be partially protected from viral killing using IRF5+IRF7 overexpression, whereas IFN pathway disruption by transfection of siRNAs to IRF5+IRF7 increases cells' vulnerability to viral infection." (PMID 22194884, 2011). "Both IRF3 and IRF7 play distinct and essential roles in the IFNα/β response to eliminate the viral infection." (PMID 22206025, 2011). "Taken together, these findings support the idea that NF-κB and c-Jun sustain basal/early ifnβ expression, while IRF-3 and IRF-7 instead dominate IFN-β production following virus infection." (PMID 22022260, 2011). "Activation of IFNβ gene expression requires IRF3, IRF7 and NFκB, but we find that the levels of IRF7 and p65 remain relatively constant during the course of viral infection." (PMID 21677781, 2011).
viral infection (continued). "Our results demonstrated that the increased susceptibility to viral infection is mediated by epigenetic mechanisms down-regulating key antiviral defense pathway regulators IRF5 and IRF7." (PMID 22194884, 2011). "Activation of IRF-3 or IRF-7 is a critical step during virus infection, promoting the most potent type I IFN production." (PMID 21936899, 2011). "Recent studies employing IRF-7 deficient (IRF-7−/−) mice demonstrated that type-1 IFN induction is severely impaired in the deficient mice and these mice are vulnerable to viral infection." (PMID 20485504, 2010). "This combined with its potential to inactivate IRF-7, obviously places this protein at a much higher pedestal compared to others in immune evasion immediately following primary viral infection." (PMID 20485504, 2010). "Production of high levels of IFN-I by pDCs in response to TLR7 or 9 ligation is entirely dependent on IRF7—this transcription factor is thus a “master regulator” of systemic production of IFN-I during virus infections." (PMID 21994626, 2010). "Accordingly the low level of endogenous IRF-7 (in uninfected cells) subsequent to the viral infection gets activated by phosphorylation and translocates to the nucleus mediating the initial phase induction of type I IFN." (PMID 20485504, 2010). "Regulation of IRF7 stability is a potent mechanism of controlling type I IFN production in response to viral infection and has previously been shown to be highly cell specific." (PMID 20668674, 2010). "Supporting the view that SUMOylation is involved in the IFN transcription, we recently reported that IRF3 and IRF7 are modified by SUMO1 through SUMO3 in fibroblasts after viral infection." (PMID 19557165, 2009). "The idea that VP35 makes use of the cellular SUMO system is further supported by our recent report that both IRF3 and IRF7 are SUMOylated following viral infection." (PMID 19557165, 2009). "This transcription factor IRF7 has been found to be directly involved in immune response to viral infections by activating IFN-α/β genes." (PMID 19229310, 2009). "Although activation of IRF7 is critical for IFN production, IRF7 expression is barely detected during the initial stage of viral infection." (PMID 19479062, 2009). "The upstream molecular mechanisms resulting in the activation of IRF-1 and IRF-7 during viral infection have begun to be elucidated in recent years." (PMID 19404407, 2009). "Because MEF have been studied extensively in virus infection-host immune response assays, we initially evaluated the effect of an IRF-3 × IRF-7 deficiency in these cells." (PMID 19798431, 2009). "As IRF-3 and IRF-7 are key regulators of the type I IFN response to viral infection, we also compared the DKO phenotype with congenic IFN-αβR−/− mice." (PMID 19798431, 2009). "The group includes genes of the innate response to viral infection that are interferon induced (ISGs): examples of this group include the six 2′-5′-oligoadenylate synthetase (Oas) genes, the Mx1 and Mx2 genes, Irf7 and Pkr." (PMID 18927629, 2008). "IRF7 is part of the pathway activated by viral infection to induce the production of IFN type I (IFNtα/β) by a positive feedback loop." (PMID 17490473, 2007). "IRF-7 has been studied extensively in viral infection and can induce the gene expressions of interferon and cytokine." (PMID 16083514, 2005). "Nonetheless, the mechanisms governing IRF7 inactivation in response to viral infection remain largely unknown." (PMID 41774756, 2026). "The expression of IRF7-induced IFN-β plays a crucial role in preventing viral infections." (PMID 40108733, 2025). "Notably, Gbp4−/− deficient mice alone showed increased serum IFN-α, consistent with Gbp4’s reported role in negatively regulating IFN-α via IRF7 during viral infection." (PMID 40607809, 2025).
viral infection (continued). "We detected elevated expression of IFN-inducible Oas-1a/g and Irf-7 in mother’s lungs at the mRNA level after childbirth, corresponding to 5–7 days after influenza infection, and indicating the innate immune response activation in response to viral infection." (PMID 41567998, 2025). "It has been demonstrated that IRF7 has a central role in maintaining and amplifying the production of high levels of IFNs during the advanced phase of the viral infection and that this role is relevant against virus latency and reactivation during chronic infections." (PMID 38932312, 2024). "The binding of AIP and IRF7 was validated and shown to increase during virus infection." (PMID 38479600, 2024). "However, previous studies have primarily concentrated on investigating the role of IRF7 in viral infection and immune response." (PMID 39118300, 2024). "Previous studies have shown that the type I interferon-IRF7 axis can mediate the transcription of the USP25 gene after viral infection or lipopolysaccharide treatment and that miRNA-200c can reduce both the messenger RNA and protein levels of USP25 in non-small cell lung cancer." (PMID 39395794, 2024). "Also, a transcriptome study of neuron cultures after viral infection detected upregulation of Ccl4, Cxcl10, Oas1, Irf1, and Irf7, an important modulator of the type I interferon process." (PMID 38189117, 2024). "Interestingly, at the later stages of viral infection, the expression of IRF7 is significantly elevated via a positive feedback loop, in which type I IFNs induce IRF7 and IRF7 then induces expressions of several IFNα subtypes, such as IFNα2, α5, α6, and α8." (PMID 38257800, 2024). "This knowledge could potentially be exploited to fine-tune the activation of IRF7 to either promote type I IFN expression in the setting of virus infections or inhibit type I IFN in certain autoimmune diseases." (PMID 38043800, 2023). "Furthermore, viral infection increased the mRNA expression of cytokines (Il6, Tnf), chemokines (Cxcl10, Ccl2), and interferon-responsive genes (Ifnb1, Ifit3, Irf7, Gbp5 and Isg15)." (PMID 37081549, 2023). "In conclusion, IRF7 plays a predominantly resistant role in bacterial and viral infections and has both a facilitative and inhibitory role in parasitic infections, which may be related to the different cells or signaling pathways." (PMID 37251373, 2023). "A study on IRF7 modulation by viral infections in Asian sea bass demonstrated that high transcript abundance was observed 24 h post infection in the brain, heart, kidney and spleen and irf7 was highly expressed 3 dpi in sea bass correlated with the transcription of mxA and isg12." (PMID 38068937, 2023). "IRF7 expression is usually low but increases markedly after viral infection." (PMID 37446070, 2023). "The importance of IRF3 and IRF7 for the survival of viral infections is controversial." (PMID 37737190, 2023). "It was previously shown that Irf7−/− mice are highly vulnerable to viral infections." (PMID 37737190, 2023). "On the one hand, IRF7 is protective against viral infection." (PMID 37638030, 2023). "In mouse models, experiments show that IRF7 –/– mice are unable to generate a type I IFN response, and in adult humans, reports of single-gene variants in IRF7 have been associated with severe presentation of common viral infections." (PMID 37097753, 2023). "Meanwhile, the transcriptional and translational levels of RIG-I, IRF3, IRF7, and NF-κB in the lung tissues were significantly increased in response to viral infection, while the treatment of baicalin significantly decreased the expression and production of these genes." (PMID 37089926, 2023). "Our experiments revealed that loss of IRF7 expression does not lead to increased viral infection of microglia." (PMID 37737190, 2023). "Also, the IRF3/IRF7 heterodimer is commonly known to be involved in viral infection, inflammatory diseases." (PMID 34996392, 2022).
viral infection (continued). "It is not only IRF7 that responds to viral infection, as this is also common to a group of interferon-stimulated genes (ISG), such as Orthomyxovirus resistance gene (Mx), oligoadenylate synthetase (OAS), ISG15, and Interferon-induced transmembrane protein 2 (IFITMs)." (PMID 36164603, 2022). "ISGs, downstream of interferon-regulatory factor 7 (IRF-7), were also associated with a robust humoral response to most of the vaccines except vaccines using poxvirus vectors such as the smallpox or yellow fever vaccines, for which strong expression of ISGs were associated with hyporesponse." (PMID 36316476, 2022). "Moreover, we also employed the anti‐IRF7 antibody to pulldown the endogenous IRF7 and assessed the ubiquitin modification of IRF7 from livers in wild type or Neurl3−/− mice following viral infection." (PMID 35792897, 2022). "Furthermore, both cGAS and IRF7 were upregulated in MIV and MgIV groups, suggesting that the type 1 interferon pathway was activated due to the transcription of cGAS and IRF7 triggered in response to viral infection." (PMID 36016774, 2022). "From these findings, it could be inferred that, even though there would be some responses from the host cells after viral infection, the virus would be able to propagate more efficiently in this IRF7−/− than in wildtype MDCK cells." (PMID 36164603, 2022). "IRF7 and NF-κB have similar functions; an important regulator of the innate immune response is activated by phosphorylation after viral infection and translocates into the nucleus after homologous dimerization or allodimerization to initiate transcription expression of inflammatory factors." (PMID 35402297, 2022). "The surprising discovery that RAGE ligands also regulated expression of IRF7 has opened new doors to probing if RAGE plays important roles in response to viral infections and the understanding that RAGE is a receptor for multiple classes of DAMPs emitted from the cytoplasm or damaged mitochondria." (PMID 35811725, 2022). "Our results thus demonstrate that IRF7 selectively interacts with NEURL3 during viral infection." (PMID 35792897, 2022). "IRF3 and IRF7 are the most important regulators of type I IFN against viral infection." (PMID 36330521, 2022). "IRF7 is critical for the host innate immune response against viral infection." (PMID 35792897, 2022). "Therefore, we evaluated the role of IRF7 in the antigen presentation capability of HCEn cells to combat viral infections." (PMID 34389779, 2021). "IRF7 can also dimerize with IRF5 through the DNA-binding domain after viral infection." (PMID 34506605, 2021). "Moreover, EV-71 3Cpro activity was described as capable to cleave Interferon Regulatory Factor 7 (IRF-7) inhibiting its ability to transactivate IFN-β expression by its phosphorylated form during early phase of viral infection." (PMID 32839386, 2020). "Virus infection led to the activation of microglia in infected wildtype and Irf-7−/− mice." (PMID 32951602, 2020). "Therefore, the IFNs induced IRF7 response and IRF7 activation by viral infection provide a positive feedback for further IFNs production." (PMID 32046242, 2020). "IRF7 was originally identified in 1997, and subsequent studies have demonstrated that it was a master regulator of type I interferon induction and of the interferon response gene expression against virus infections." (PMID 32437400, 2020). "Furthermore, while certain genes were repressed during both virus infections (e.g., Irf7 or Ifnb1), expression of others was more prominently reduced upon H5N1 infection (e.g., IL-1β, IL-6, Ccl2)." (PMID 32231671, 2020). "Basically, type I interferon signals or a virus infection are typical IRF7 inducers." (PMID 32437400, 2020). "Thus, sensing of infection by BMD cells via cGAS and IRF7 is critical for resistance to a lethal viral disease in a natural host." (PMID 31877196, 2019).
viral infection (continued). "In addition to IRF3, other IRFs have been involved in the amplification of type I IFN response following viral infection: IRF7 plays an instrumental role whereas IRF1 and IRF5, are reported to be dispensable for inducing type I IFN." (PMID 31319869, 2019). "Such negative regulation may help to avoid hyper-inflammatory responses induced by the over-activated IRF7-mediated type I interferons at late stage of the viral infection." (PMID 31603949, 2019). "In detail, Irf7 displayed by far the highest gene expression during acute viral infection." (PMID 29538462, 2018). "To address how this IRF7- and IFN-I-restricted response to DENV may position pDCs as critical in the control of viral infections, we generated a unique mouse model where IRF7 signaling is restricted to pDCs." (PMID 29914621, 2018). "In addition, a high rate of induced cell death was observed due to elevated level of IRF7 upon viral infection." (PMID 30356848, 2018). "IRF-3 and IRF-7 could induce IFNs expression as interferon regulatory factors by nuclear-translocation upon virus infection." (PMID 30319633, 2018). "However, in contrast to constitutively expressed IRF3, the basal expression level of IRF7 is minimum but is strongly induced by type I IFN-mediated responses in an autocrine feedback loop after virus infection (discussed in detail below)." (PMID 30671058, 2018). "In addition, Irf7 showed an increased gene expression at the chronic disease stadium 28 days after viral infection when compared to their healthy controls." (PMID 29538462, 2018). "Furthermore, examination of IFN and ISGs mRNA transcripts in cells infected with FMDV S fragment mutant demonstrated an upregulation of Mx-1, IFNβ, IL-6, TNFα, and IRF7 when compared to WT virus infection." (PMID 30483224, 2018). "In our recent analysis of stable overexpression and knockdown of IRF7 in chicken DF-1 cell lines followed by mimicking viral infection with dsRNA analog poly(I:C), we demonstrated that the primary function of IRF7 as type I IFN regulator may be conserved." (PMID 30356848, 2018). "Further knockdown of IRF3 or IRF7 enhanced M1 virus infection in HCT-116 cells." (PMID 29670091, 2018). "Dpo significantly enhanced the induction of IRF7 during viral infection." (PMID 29124042, 2017). "The transcription factor IRF7 plays a crucial role in the regulation of type I interferon response to viral infections, so we predicted the significant induction of IRF7 mRNA expression (>70-fold increase) in 76-9 cells that was observed following treatment with oncolytic virus." (PMID 27966453, 2017). "We propose that, analogous to the severe course of primary influenza infection due to biallelic deficiency of a downstream effector, IRF7, homozygous loss of IFIH1 defines a novel Mendelian immunodeficiency disorder that increases susceptibility to severe viral infections." (PMID 29018476, 2017). "Thus, IRF3 is essential for the induction of IFN-β as an early response to virus infection and IRF7 leads to the amplification signals of IFN-α genes." (PMID 29053748, 2017). "In addition, miR-23 induced type I IFN expression through activation of IRF3/IRF7, whichmight further inhibit virus infection." (PMID 28977918, 2017). "Furthermore, IRF7 is constitutively expressed (and induced following virus infection) in primary macrophages and macrophage cell-lines like RAW 264.7 cells." (PMID 28018859, 2016). "In contrast, IRF7 level was markedly repressed by Bcl6 overexpression and boosted by Bcl6 deletion in macrophages during viral infection, suggesting that selective regulation of IRF7 expression may contribute to Bcl6-mediated RIG-I signaling modulation." (PMID 26728228, 2016). "Among all the IRFs, IRF3 and IRF7 are the key regulators of IFN-I expression upon viral infection." (PMID 25759845, 2015).